PGK1 (phosphoglycerate kinase 1)
Diseases named in the same sentence as PGK1 in open-access papers (continued):
Sharing a sentence is not in itself a finding about the gene and the disease.
tumor (continued). "Although HIF-1α, PGK1 and VEGF tended to be lower in tumours with above median ascorbate, significance was not reached." (PMID 35419292, 2022). "However, only two tumors formed in shPGK1+Myc-PRAS40 T246A group, and the tumor volume and weight were downregulated greatly compared to that of the shPGK1+Myc-PRAS40 group (P < 0.05), but not different from that of the PGK1-knockdown group." (PMID 35058442, 2022). "Similarly, treatment with LoVo cells with EVs secreted by mouse xenograft tumours‐isolated TANs, but not with those from murine PNs, elevated the expression levels of HK2 and PGK1, while silencing of Spi1 in TANs prevented these changes." (PMID 34841706, 2021).
cancer (211 papers, 2006 to 2026). A tumor composed of atypical neoplastic, often pleomorphic cells that invade other tissues. "As a key enzyme in glycolysis, PGK1 plays a central role in the Warburg effect, which is a hallmark of cancer metabolism." (PMID 40771921, 2025). "Considering the association of cancer stemness with metastasis and recurrence, we investigated the expression of PGK1 and MYH9 in recurrent and metastatic ESCC tissues." (PMID 40534132, 2025). "Previous studies have shown that Previous studies have shown that PGK1 is associated with the development and progression of many types of cancers, as well as chemoradiotherapy resistance." (PMID 40464853, 2025). "As a key enzyme in the glycolytic pathway, phosphoglycerate kinase 1 (PGK1) has been linked to the progression of various cancer types." (PMID 40771921, 2025). "We discovered that PGK1 was a significant risk factor for overall survival across diverse cancer types, including NSCLC." (PMID 38163864, 2024). "Further in vivo functional experiments demonstrated that substituting endogenous PGK1 with a mitochondrial translocation-deficient mutant, PGK1 S203A, inhibited cancer cell proliferation and induced apoptosis." (PMID 39590319, 2024). "PGK1 variants expressed in cancer cells show different catalytic activities compared with the conformational stability of natural enzymes." (PMID 37723547, 2023). "Elevated expression of PGK1 has been already associated with chemotherapy and radiotherapy resistance and poor prognosis in multiple types of cancer." (PMID 37654625, 2023). "In this manuscript, we discussed the effects of the structure, function, molecular mechanisms underlying PGK1 regulation on the initiation and progression of cancer." (PMID 37723547, 2023). "As recently reviewed, a high expression of phosphoglycerate kinase 1 is positively associated with chemoresistance in all cancer models explored so far." (PMID 37376060, 2023). "Recently, metabolic reprogramming proteins, especially PGK1, have been highlighted as an emerging hallmark of cancer, and our study had two striking findings in the analysis of PGK1 in aUC." (PMID 36292976, 2022). "We investigated the association between PGK1 expression and the clinical traits of LUAD patients in the TCGA data sets, in order to learn more about the significance and underlying processes of PGK1 expression in cancer." (PMID 36358653, 2022). "The results indicated that PGK1 expression was associated with poor prognosis in a variety of cancers, including LUAD." (PMID 36358653, 2022). "Association between PGK1 expression and immune checkpoints was analyzed at the mRNA levels across pan-cancer." (PMID 34790279, 2021). "Loss of PTEN function in cancer cells causes augmented PGK1 autophosphorylation, glycolysis, and ATP production, induction of cancer cell proliferation, and tumorigenesis." (PMID 32708484, 2020). "It has been demonstrated that high expression and activity of PGK1 was associated with poor prognosis in several types of cancer." (PMID 32070368, 2020). "What’s more, we have observed that decreased ubiquitination and increased stability of the metabolic related molecules, such as PDK1, NRF2, ULK1 and phosphoglycerate kinase 1, are associated with chemoresistance in various cancers." (PMID 33004065, 2020). "All these findings suggest that PGK1 gene modification and PGK1-mitochondrial function were significantly associated with clinical behaviors of cancer patients." (PMID 31578148, 2019). "Another intriguing link between the ERK1/2 signaling and cancer-associated Warburg effect is provided by the glycolytic enzyme phosphoglycerate kinase 1 (PGK1)." (PMID 30487597, 2019). "In this study, we selected from the COSMIC database some somatic PGK1 single nucleotide variants found in cancer tissues." (PMID 29995887, 2018). "In this study we analyzed the effect of the single nucleotide variants found in cancer tissues on the PGK1 structure and function." (PMID 29995887, 2018).
cancer (continued). "ENO1 and PGK1, linked to aerobic glycolysis, are correlated with the cancer prognosis." (PMID 41328179, 2026). "Therefore, targeting PGK1 and its associated molecular pathways involved in lactate metabolism represents a promising therapeutic strategy for cancer treatment." (PMID 38993561, 2024). "Additionally, PGK1 is linked to cancer patients' poor prognoses and resistance to chemotherapy and radiation therapy." (PMID 38577592, 2024). "PGK1 is also associated with chemoradiotherapy resistance and poor prognosis of cancer patients." (PMID 39695074, 2024). "Therefore, abnormal expression of PGK1 affects cell proliferation, differentiation, apoptosis, autophagy, migration, invasion, and DNA repair, which are closely associated with cancer initiation, development, metastasis, angiogenesis and drug resistance." (PMID 37723547, 2023). "A study examining PGK1 messenger RNA (mRNA) levels and DNA methylation in normal and 34 types of cancerous tissues has shown that PGK1 mRNA expression decreases following the hypomethylation of its promoter region, and this is associated with poor prognosis in several cancer types, including HCC." (PMID 36769116, 2023). "By regulating the ATP and 3-PG levels, PGK1 plays an important role in coordinating energy metabolism, biosynthesis and redox balance, so mutations in PGK1 can be responsible for changes in the metabolic spectrum in different cancers." (PMID 37723547, 2023). "As a gene activated by increased oxidative stress and vascular damage, PGK1 has been linked to a wide range of diseases, including Parkinsonism, hereditary non-spherocytic hemolytic anemia, neurological impairment, myopathy, and malignant tumors." (PMID 36358653, 2022). "PGK1 is also associated with chemoradiotherapy resistance and poor prognosis in cancer patients." (PMID 36358653, 2022). "Association of PGK1 with MSI was then evaluated in different cancer types." (PMID 34790279, 2021). "Since gracillin displays no obvious toxicity in normal cells derived from various organs and in mice, it is possible that gracillin may suppress specifically increased forms of PGK1, such as those modified posttranslationally or mutated, in cancer cells." (PMID 32276500, 2020). "High expression of PGK1 is associated with poor prognosis of cancer patients." (PMID 33344462, 2020). "In addition, we revealed a high percentage of patients exhibiting elevated protein kinase activity of PGK1 compared to a relatively low IDH1 mutations in cancer patients." (PMID 31578148, 2019). "By controlling ATP and 3-PG levels, PGK1 plays an important role in coordinating energy production with biosynthesis and redox balance, so mutations of this enzyme can be responsible for alterations of metabolic profile in different cancer cell lines." (PMID 29995887, 2018). "In the present study, we found another metabolism reprogramming mediated by PGK1 protein kinase activity-dependent phosphorylation, which was associated with clinical behaviors of cancer patients and was an independent prognostic biomarker in multiple types of cancer." (PMID 31578148, 2019). "Phosphoglycerate kinase 1 (PGK1) is established as an oncogenic driver in malignant tumor progression." (PMID 42183839, 2026). "These pan-cancer observations suggest that the PGK1/MORC2 pathway represents a shared mechanism of radioresistance across multiple solid tumors." (PMID 41213904, 2025). "As previously discussed, both ALDOC and PGK1 are glycolysis-related proteins known to significantly regulate aerobic glycolysis in malignant tumors." (PMID 40518543, 2025). "PGK1, a key rate‐limiting enzyme in glycolysis, plays a critical role in cancer cell metabolic adaptation and survival through phosphorylation‐dependent mechanisms." (PMID 40529105, 2025). "For instance, studies have shown that inhibition of PGK1 (phosphoglycerate kinase 1) phosphorylation suppresses glycolysis, tumorigenesis, and cell proliferation in various cancers." (PMID 40427728, 2025).
cancer (continued). "This highlights PGK1's role as a protein kinase in coordinating glycolysis and the tricarboxylic acid cycle, which is critical for cancer metabolism and tumorigenesis." (PMID 40016971, 2025). "PGK1 is overexpressed in various cancer types, promoting aerobic glycolysis, cancer cell proliferation, and metastasis." (PMID 40016971, 2025). "In cancer research, PGK1 has been widely studied due to its frequent overexpression in cancer cells, which likely supported their rapid proliferation." (PMID 39712033, 2024). "But the enzyme activity of PKM2 in cancer cells is very low, thus PGK1 plays a more important role in regulating glycolysis metabolism in cancer cells." (PMID 39695074, 2024). "The increased acetylation of PGK1 at K323 has been identified as a critical oncogenic mechanism, enhancing its role in cancer progression." (PMID 38997696, 2024). "We found that sLZIP plays an important role in cancer proliferation and growth through transcriptional regulation of PGK1." (PMID 39594816, 2024). "PGK1 is essential for the continuation of glycolysis to support the rapid proliferation of cancer cells." (PMID 39594816, 2024). "PGK1 has been reported to promote cancer cell proliferation and migration in NSCLC through the downstream ERK/MCM4 pathway." (PMID 38674080, 2024). "Recent studies suggest that increased PGK1 activity plays a role in cancer metastasis and invasiveness." (PMID 39594816, 2024). "PGK1 catalyzes the first ATP production step during aerobic glycolysis, allowing cancer cells to maintain glycolytic flux and support the anabolic production of biomolecules for uncontrolled proliferation, especially under hypoxic conditions." (PMID 39594816, 2024). "As a major member of HIF-1α signaling pathway, it has been proved that PGK1 is directly regulated by HIF-1α in many cancers." (PMID 39695074, 2024). "This is crucial for revealing the role of PGK1 in metabolic diseases and cancer, as well as its potential in therapeutic applications." (PMID 39590319, 2024). "The previous research showed that PGK1 can promote the proliferation of cancer by turning on the AKT/mTOR pathway in non-small-cell lung cancer." (PMID 37821504, 2023). "We investigated the single nucleotide variations (SNVs) of HFRS genes in different cancers and observed that some genes (CCT6A, TF, KRT14, P4HA2, PGK1, SLC16A2, and STC2) were frequently mutated in COAD, STAD, UCEC, and SKCM." (PMID 36998462, 2023). "PGK1 plays an important role in the progression of cancer through its involvement in the regulation of cancer cell proliferation and tumorigenesis, while TIGAR inhibits glycolysis and protect cells from ROS-associated apoptosis." (PMID 36919762, 2023). "Intracellular PGK1 seems to play contradictory and even opposite roles compared with extracellular PGK1 in cancer occurrence." (PMID 37723547, 2023). "Collectively, our study indicated that PGK1 is an important drug target in ESCC, whereas the association of the expression and phosphorylation levels of PGK1 with other kinds of cancer requires further investigation." (PMID 36966136, 2023). "PGK1 has multi-faceted roles in addition to cell metabolism regulation and is correlated with chemotherapy resistance and poor prognosis in most cancers." (PMID 37176148, 2023). "In non-small lung cancer, evidence has been reported that PGK1 regulates cancer metastasis by binding to HTATSF1." (PMID 37958393, 2023). "In gallbladder cancer cells, downregulated STUB1 leads to the overexpression of PGK1, followed by cancer proliferation and metastasis." (PMID 37176148, 2023). "We further investigated the effects of the interplay and the underlying mechanisms between circ‐CTNNB1 and RBM15 on the regulation of target genes (GPI, HK2 and PGK1) and cancer progression in OS cells." (PMID 36181462, 2023). "At the same time, the high expression of PGK1 is found in multiple cancers and is corrected with the poor prognosis of cancer." (PMID 36949536, 2023).
cancer (continued). "A pan-cancer analysis of PGK1 expression levels showed that PGK1 was highly expressed in BC relative to normal tissues." (PMID 36860848, 2023). "PGK1 has a significant role in sustaining cellular homeostasis and autophagy, making it an attractive molecular target for cancer therapy." (PMID 37190124, 2023). "A comprehensive understanding of the role of PGK1 in cancer progression will facilitate the development of better diagnosis and treatment strategies." (PMID 37723547, 2023). "This suggests that PGK1 can enhance the ability of immune cells to recognize and bind to antigens, thus enhancing cancer cell elimination." (PMID 37723547, 2023). "PGK1, a downstream target of miR-628-5p screened by various methods, has been widely reported to assume a decisive role in aerobic glycolysis in cancer cells." (PMID 38098044, 2023). "In colorectal cancer (CRC), miR-548-5p influences the proliferation and function of CRC cells by targeting PGK1 and thus plays a cancer-suppressing role." (PMID 37723547, 2023). "Collectively, these studies suggest that PGK1 is an effective target to prevent cancer invasion and metastasis as well as cancer progression." (PMID 37723547, 2023). "For most human cancers, PGK1 acts as an oncoprotein by activating several proliferative and antiapoptotic signalling cascades to promote tumorigenesis, metastasis, and drug resistance." (PMID 37723547, 2023). "Following the paradigm of PFK1 and PKM2, the O-GlcNAcylation of phosphoglycerate kinase 1 (PGK1) was investigated in a cancer model." (PMID 36359905, 2022). "Recently, PGK1 has gradually become a hot topic in cancer research due to its involvement of a variety of biological activities." (PMID 35121728, 2022). "Phosphoglycerate kinase 1 (PGK1) is related to the progression of many cancers and is an important enzyme in glycolysis." (PMID 35392171, 2022). "PGK1 had been reported as a major enzyme in the aerobic glycolysis pathway to induce cancer progression." (PMID 35493305, 2022). "Nevertheless, similarly to G6PD, PFK1 and PKM2, PGK1 O-GlcNAcylation favors cancer cell proliferation and promotes tumorigenesis." (PMID 36359905, 2022). "PGK1 has a complicated and double-edged function as an oncogene or tumor suppressor in cancer occurrence and progression." (PMID 35121728, 2022). "To identify the prognosis value of PGK1 expression, we used GEPIA2.0 to analyze the relationship between the expression of PGK1 and pan-cancer overall survival (OS)." (PMID 36358653, 2022). "Our study is anticipated to be able to offer novel insights in understanding PGK1/PRAS40 signaling hyperactivated cancers." (PMID 35058442, 2022). "PGK1, which catalyzes the conversion of 1,3-diphosphoglycerate to 3-phosphoglycerate, yielding ATP, was found to be O-GlcNAcylated in cancer cells." (PMID 36359905, 2022). "RNA-sequencing data from TCGA data were used to analyze the mRNA expression profile of PGK1 in a pan-cancer context." (PMID 36358653, 2022). "PGK1 was previously reported to induce autophagy by phosphorylating Beclin1 under glutamine deprivation or hypoxia in cancer." (PMID 35058442, 2022). "The development of specific PGK1 inhibitors through virtual screening, compound modification even de novo synthesis and their application in the treatment of PGK1-related cancers are going on the way." (PMID 35121728, 2022). "As well-known, PGK1 is a glycolytic kinase that activates intracellular glycolysis to provide ATP for the rapid growth of cancer cells." (PMID 35121728, 2022). "For example, the functions of intracellular and extracellular phosphoglycerate kinase 1 (PGK1) differ in cancer progression." (PMID 36102516, 2022). "The combined control of PGK1 on glycolysis, mitochondrial metabolism, and autophagy drive malignant tumor progression, according to previous studies." (PMID 36358653, 2022).